PTPN22 (protein tyrosine phosphatase non-receptor type 22)
Diseases named in the same sentence as PTPN22 in open-access papers (continued):
Sharing a sentence is not in itself a finding about the gene and the disease.
skin cancer (2 papers, 2024). "Other examples of pleiotropic variants include rs2476601, a non-synonymous variant in PTPN22 which we found to be causally associated with multiple autoimmune diseases and their treatments as well as skin cancer, with the autoimmune-protective allele increasing risk of cancer." (PMID 38997278, 2024). "This is particularly important because predicted beneficial effects of targeting a protein may be countered by on-target side effects on other traits, as we saw where the autoimmune-protective variant in PTPN22 was associated with an increased risk of skin cancer." (PMID 38997278, 2024).
thymoma (2 papers, 2014 to 2025). A neoplasm arising from the epithelial cells of the thymus. "In subsequent studies on Swedish, German and Hungarian MG patients, this PTPN22 variant was associated with AChR-MG and with thymoma-associated MG (TAMG) in one study." (PMID 25119822, 2014). "Based on the recently performed meta-analyses and genome-wide results, the most robust conclusion is that the minor allele (T) of PTPN22 polymorphism is associated with the presence of anti-AChR Abs and with the absence of thymoma in MG." (PMID 25119822, 2014). "Furthermore, studies indicate that the PTPN22 T allele polymorphism is associated with non-thymoma MG in the absence of anti-titin antibodies." (PMID 40565966, 2025).
uveitis (2 papers, 2013 to 2014). An inflammatory process affecting a part of or the entire uvea. "Very recently, our group revealed that PTPN22 gene polymorphism did not confer risk for ocular Behcet's disease, but the role of PTPN22 gene polymorphisms in other uveitis entities such as AAU+AS+ and VKH syndrome in Chinese Han was not yet clear." (PMID 24816862, 2014). "Allelic and genotype frequencies of PTPN22 genetic variants in overall uveitis patients, uveitis patients stratified according to the anatomic classification and healthy controls from Spanish population." (PMID 23559857, 2013). "The lack of an association between PTPN22 polymorphisms with both AAU+AS+ and ocular Behcet's disease suggests that the PTPN22 association with uveitis may be confined to those entities that involve an autoimmune pathogenesis." (PMID 24816862, 2014). "In addition, since the two analyzed polymorphisms are independent and both are separately relevant for the PTPN22 function, uveitis can be either the consequence of mutations present simultaneously in both genetic positions or, alternatively, in only one." (PMID 23559857, 2013). "PTPN22 allelic combinations (rs2476601-rs33996649) in uveitis patients and healthy controls from Spanish population." (PMID 23559857, 2013). "Why certain uveitis entities are associated with PTPN22 gene polymorphisms and others are not remains unclear." (PMID 24816862, 2014). "The lack of association between the PTPN22 gene and this disorder suggests that the PTPN22-associated diseases share a common underlying mechanism that may not be important in the uveitis pathogenesis." (PMID 23559857, 2013). "Therefore, this lack of association of the PTPN22 polymorphisms with uveitis should be interpreted carefully." (PMID 23559857, 2013). "Therefore, our results agree with previously published results and could indicate that the PTPN22 gene does not play an important role in the pathophysiology of the different clinical forms of uveitis." (PMID 23559857, 2013).
VKH syndrome (2 papers, 2009 to 2014). "In conclusion, our results show that a functional variant rs2488457 of the PTPN22 gene is associated with an increased risk for the development of VKH syndrome by modulating the gene expression, PBMC proliferation and IL-10 production." (PMID 24816862, 2014). "In view of the multiple organ involvement in VHK syndrome and AS, further studies are needed to examine the association of PTPN22/rs2488457 with VKH syndrome and AS patients recruited from other medical departments." (PMID 24816862, 2014). "In the present study, we show that a functional variant rs2488457 of PTPN22 is associated with a higher risk for the development of VKH syndrome." (PMID 24816862, 2014). "In this study, genetic susceptibility to VKH disease was investigated by screening for single nucleotide polymorphisms (SNPs) of PTPN22." (PMID 19503742, 2009). "In the present study, we analyzed polymorphisms of the new candidate gene, PTPN22, in Japanese patients with VKH disease." (PMID 19503742, 2009). "A total of 167 Japanese patients with VKH disease and 188 healthy Japanese controls were genotyped by direct sequencing methods for six SNPs (rs3811021, rs1217413, rs1237682, rs3761935, rs3789608, and rs2243471) of PTPN22 including the uncoding exons." (PMID 19503742, 2009). "Our study showed a strong association of PTPN22/rs2488457 with VKH syndrome but not with AAU+AS+." (PMID 24816862, 2014). "Three SNPs of PTPN22 (rs2488457, rs1310182 and rs3789604) were genotyped in 302 AAU+AS+ patients, 1005 VKH syndrome patients, and 2010 healthy controls." (PMID 24816862, 2014). "The study showed that a functional variant of PTPN22 confers risk for VKH syndrome but not for AAU+AS+ in a Chinese Han population, which may be due to a modulation of the PTPN22 expression, PBMC proliferation and IL-10 production." (PMID 24816862, 2014).
Achalasia (1 paper, 2024). A disorder of esophageal motility characterized by the inability of the lower esophageal sphincter to relax during swallowing and by inadequate or lacking peristalsis in the lower half of the body of the esophagus. "Genetic risk factors within the HLA-DQ receptor, SNPs on the IL23R which regulates T cell differentiation, on PTPN22, which is a down-regulator of T-cell activation, and IL10 gene promoter were identified, emphasizing the concept of a genetically driven immune response in patients with achalasia." (PMID 39337632, 2024).
acute coronary syndrome (1 paper, 2020). Signs and symptoms related to acute ischemia of the myocardium secondary to coronary artery disease. "Upregulation of PTPN22 could result in impairment of regulatory T-cell differentiation in patients with non-ST-segment elevation acute coronary syndromes." (PMID 32536826, 2020).
allergic disease (1 paper, 2025). An immune response that occurs following re-exposure to an innocuous antigen, and that requires the presence of existing antibodies against that antigen. "GWAS data further strengthen the link between these genes and diseases, with BATF, CEBPA, and ETS1 associated with allergic diseases, and PTPN22, ETS1, PTPN11, and BATF linked to RA." (PMID 40839671, 2025).
anterior uveitis (1 paper, 2013). Inflammation of the iris and anterior chamber of the eye. "This study represents the first attempt to evaluate the possible implication of the functional variants R263Q and R620W of the PTPN22 gene in the pathophysiology of endogenous non-anterior uveitis in a well-defined cohort." (PMID 23559857, 2013). "Taking into account this evidence, in the current study we evaluated the influence of the PTPN22 R263Q and R620W polymorphisms in the genetic background of endogenous non-anterior uveitis." (PMID 23559857, 2013). "We aimed to analyze for the first time the influence of these PTPN22 genetic variants on endogenous non-anterior uveitis susceptibility." (PMID 23559857, 2013). "A minor effect of the PTPN22 gene cannot be discarded, and additional studies are required to draw stronger conclusions about the exact role of the R263Q and R620W polymorphisms in the susceptibility and clinical spectrum of non-anterior uveitis." (PMID 23559857, 2013). "Previously, the possible influence of the PTPN22 gene in anterior uveitis susceptibility was investigated without evidence of association." (PMID 23559857, 2013). "Therefore, the lack of evidence of an association between the PTPN22 gene and non-anterior uveitis might suggest the low involvement of the humoral component in non-anterior uveitis although further studies are needed." (PMID 23559857, 2013).
bladder cancer (1 paper, 2020). "To better understand the role of ECs and NAEs in bladder cancer, we analyzed gene expression data from TGCA database regarding the metabolic pathway of the ECS, comprising the synthetic enzymes (PLCB1-4, PTPN22, ABHD4, GDE1, DAGLA, DAGLB, and NAPE-PLD) and the hydrolytic ones (FAAH, NAAA, and MGLL)." (PMID 32260109, 2020).
cholestasis (1 paper, 2023). Impairment of the bile flow caused by obstruction within the liver, or outside the liver in the bile duct system. "The PTPN22 gene encodes a protein involved in regulating immune cell function, which suggests that immune-mediated mechanisms may play a role in the pathogenesis of drug-induced liver injury and cholestasis." (PMID 37324459, 2023).
chronic mucocutaneous candidiasis (1 paper, 2021). "Third, PTPN22-C1858T polymorphic patients with chronic mucocutaneous candidiasis showed a higher incidence of bacterial pulmonary infections than normal controls." (PMID 33717071, 2021).
colorectal cancer (1 paper, 2020). A primary or metastatic malignant neoplasm that affects the colon or rectum. "The expression profiles of PTPN21 in colorectal cancer and PTPN22 in stomach cancer warrant further examination." (PMID 32536826, 2020). "For colorectal cancer (CRC), PTPN2, PTPN21 and PTPN22 levels were correlated with incidence; expression of PTPN5, PTPN12, and PTPN14 was correlated with TNM stage and N stage; high PTPN5 or PTPN7 expression was associated with increased hazards of death." (PMID 32536826, 2020). "Different from these results, PTPN22 was downregulated in stomach cancer cell lines and PTPN21 were increased in colorectal cancer cell lines, which were inconsistent with the conclusions of Oncomine and Ualcan database." (PMID 32536826, 2020).
COVID-19 (1 paper, 2023). A disease caused by infection with severe acute respiratory syndrome coronavirus 2. "HLA-DRB3, CXCL13, PTPN22 and AHR were identified as genes that were commonly down-regulated in both COVID-19(+) TV and COVID-19(+) PU groups compared to the COVID-19(-) PU control group." (PMID 37026002, 2023).
dry eye (1 paper, 2025). "An analysis of polymorphic markers revealed the association of TRIM21 gene and PTPN22 gene polymorphisms with the risk of developing exogenous dry eye." (PMID 40693714, 2025).
empyema (1 paper, 2010). An accumulation of pus in a body cavity, usually the pleural space. "Common genetic variants in the immune response genes PTPN22 and NFKBIA have previously been identified in association with empyema susceptibility, although additional genes are likely to be involved." (PMID 20078874, 2010).
influenza (1 paper, 2017). An acute viral infection of the respiratory tract, occurring in isolated cases, in epidemics, or in pandemics; it is caused by serologically different strains of viruses (influenzaviruses) designated A, B, and C, has a 3-day incubation period, and usually lasts for 3 to 10 days. "Studies of larger cohorts will be needed to define the effect of PTPN22 risk allele carriage on antibody and T cell responses to influenza vaccination during pregnancy." (PMID 28723925, 2017). "We sought to quantify the effects of PTPN22-R620W on humoral and cell-mediated immune responses to the inactivated influenza vaccine among healthy pregnant women." (PMID 28723925, 2017). "We evaluated the role of PTPN22 R620W carriage in CD4 T cell responses to influenza vaccination." (PMID 28723925, 2017). "More informative studies of how genetic (e.g. PTPN22-R620W) or environmental (e.g. pregnancy) factors influence CD8 influenza vaccine responses would likely require sampling of tissues, such as lung and secondary lymphoid organs, where these cells develop and exert protective effects." (PMID 28723925, 2017). "We found no significant change in influenza-specific CD8 T cell numbers in either PTPN22 R620W carriers or non-carriers after influenza vaccination." (PMID 28723925, 2017). "Our study reports on humoral and cell-mediated influenza vaccine responses in pregnant women carrying a genetic factor that could modulate vaccination responses (PTPN22 R620W), and characterizes the viral epitope-specific CD8 T cell responses to influenza vaccine in pregnancy." (PMID 28723925, 2017). "To test this hypothesis, we measured the humoral and cell-mediated immunologic response to the inactivated influenza vaccine among healthy pregnant women who are PTPN22 R620W carriers and non-carriers." (PMID 28723925, 2017).
joint disease (1 paper, 2014). "We have previously shown that the transcript level of PTPN22.6 but not total PTPN22 in peripheral blood is correlated with the 28-joint disease activity score with three variables including C-reactive protein (DAS28-CRP3) scores in patients with RA." (PMID 24433447, 2014).
leprosy (1 paper, 2021). Leprosy is a chronic infectious disease affecting primarily the skin and peripheral nervous system. "An elevated risk of leprosy was perceived in patients with PTPN22-C1858T polymorphism in heterozygote models [CT versus CC: OR = 2.91 (95% CI: 0.99–8.60, PH = 0.094)] and dominant models [TT/CT versus CC: OR = 2.91 (95% CI: 0.99–8.60, PH = 0.094)]." (PMID 33717071, 2021). "A significantly increased risk of leprosy was perceived in patients with the PTPN22-C1858T polymorphism [C versus T: OR = 2.82 (95% CI: 1.02–7.81, PH = 0.108)]." (PMID 33717071, 2021). "However, further studies are required to validate the relevance between PTPN22-C1858T polymorphism and leprosy because of the limited quantity of studies and indicated heterogeneity among studies." (PMID 33717071, 2021).
leukemia (1 paper, 2022). A malignant (clonal) hematologic disorder, involving hematopoietic stem cells and characterized by the presence of primitive or atypical myeloid or lymphoid cells in the bone marrow and the blood. "The findings showed that PTPN6, PTPN18, and PTPN22 had higher expression levels in leukemia than in normal blood samples, while PTPN1 had a lower expression level in the former than the latter." (PMID 36699453, 2022).
liver fibrosis (1 paper, 2017). "This included genes associated with metabolism (Fabp1, Insr), genes associated with cell stress (Atf6, Ddit3, and Eif2ak3), genes associated with liver fibrosis (Hgf, Sp1, and Timp1) and genes associated with the inflammatory response (Tnf, Ptpn22, and Pparg)." (PMID 28686204, 2017).
lung carcinoma (1 paper, 2022). "Here, we used two different comprehensive bioinformatics analysis and revealed protein tyrosine phosphatase non-receptor type (PTPN) family genes, especially PTPN1 and PTPN22, were downregulated in lung cancer tissue in comparison with normal samples." (PMID 36556168, 2022).
lymph node metastasis (1 paper, 2016). "PTPN22 expression was inversely correlated with lymph node metastasis and TNM stage." (PMID 27613842, 2016).
malabsorption syndrome (1 paper, 2016). A syndrome resulting from the inadequate absorption of nutrients in the small intestine. "In UC the AA and GA genotype was associated with increased use of azathioprine and anti-TNF antibodies, but significantly less patients with the PTPN22 variant featured malabsorption syndrome (p = 0.026)." (PMID 27467733, 2016). "Although no disease-promoting association of the PTPN22 SNP rs2476601 with UC was described before, we demonstrated, that significantly fewer UC patients carrying the variant developed malabsorption syndrome, but vitamin D and calcium deficiency was more common." (PMID 27467733, 2016).
Meniere disease (1 paper, 2014). A disease of the inner ear (labyrinth) that is characterized by fluctuating sensorineural hearing loss; tinnitus; episodic vertigo; and aural fullness. "Genes that were revealed to be associated with bilateral Meniere's disease, chronic balance/hearing loss were allelic variants of DRB1, PTPN22, TLR 10, MICA genes." (PMID 25330336, 2014).
mycobacterial infection (1 paper, 2021). "First, we applied subgroup analysis to demonstrate the differences in the correlation between PTPN22-C1858T polymorphism and increased risk of mycobacterial infection." (PMID 33717071, 2021). "Herein, we performed this meta-analysis to systematically summarize and articulate the correlation between PTPN22-C1858T polymorphism and the risk of mycobacterial infection." (PMID 33717071, 2021). "leprae) was able to account for the heterogeneity of the associations between mycobacterial infections and PTPN22-C1858T polymorphism." (PMID 33717071, 2021). "Herein, we carried out this meta-analysis to systematically summarize and articulate the correlation between PTPN22-C1858T polymorphism and mycobacterial infection." (PMID 33717071, 2021). "We explored that PTPN22-C1858T polymorphism associates susceptibility to mycobacterial infection." (PMID 33717071, 2021). "In Caucasians, the result indicated that PTPN22-C1858T polymorphism correlates the susceptibility to mycobacterial infection [C versus G: OR = 1.02 (95% CI: 0.22–4.70, PH = 0.001); CT versus CC: OR = 1.03 (95% CI: 0.21–4.97, PH = 0.001); CT+TT versus CC: OR = 1.03 (95% CI: 0.21–4.97, PH = 0.001)]." (PMID 33717071, 2021). "Multivariate meta-regression analysis of PTPN22-C1858T in patients with mycobacterium infection." (PMID 33717071, 2021).
myositis (1 paper, 2018). "A large scale immunochip study has shown that PTPN22, UBE2L3, CD28, TRAF6, and STAT4 are associated with myositis of Caucasian descents: PTPN22 was primarily associated with PM." (PMID 29854780, 2018).
Nephropathy (1 paper, 2014). A nonspecific term referring to disease or damage of the kidneys. "In the present study association between nephropathy and PTPN22 1858C>T gene polymorphism is at the limit of statistical significance." (PMID 24985973, 2014).
non-melanoma skin carcinoma (1 paper, 2022). "For example, the carriers of the PTPN22(C1858T) variant have a lower risk of non-melanoma skin cancer, while the homozygotes for the PTPN22(C1858T) have improved survival when treated with atezolizumab (anti-PDL1 antibody)." (PMID 35634292, 2022).
pancreatic ductal adenocarcinoma (1 paper, 2022). An infiltrating adenocarcinoma that arises from the epithelial cells of the pancreas. "In Iacobuzio-Donahue dataset, we found that PTPN22 expressed higher in PAAD (fold change = 2.770), and, in Buchholz data, PTPN22 expressed higher in pancreatic ductal adenocarcinoma (fold change = 126.456), pancreatic intraepithelial neoplasia (fold change = 4.571) versus normal samples." (PMID 35154122, 2022).
penicillin allergy (1 paper, 2020). "In the present study, we identify associations of the HLA-B∗55:01 allele and a missense variant rs2476601 in PTPN22 with self-reported penicillin allergy using data from four large cohorts: UKBB, EstBB, BioVu, and 23andMe." (PMID 32888428, 2020).
peritonitis (1 paper, 2016). Inflammation of the peritoneum (tissue that lines the abdominal wall and covers most of the organs in the abdomen). "In contrast, in vivo neutrophil recruitment following thioglycollate-induced peritonitis and in vitro chemotaxis were not affected by lack of PTPN22." (PMID 27807193, 2016).